MLKL (mixed lineage kinase domain like pseudokinase)
Diseases named in the same sentence as MLKL in open-access papers (continued):
Sharing a sentence is not in itself a finding about the gene and the disease.
tumor (continued). "Our findings in human tumor samples that MLKL and RIPK3 gene expression levels were upregulated during ICI treatment suggest a potential positive feedback loop by infiltrating immune cells which might further enhance necroptotic signaling in the TME." (PMID 40345706, 2025). "Next, IHC staining in serial sections of HNSCC patients showed that p-MLKL level was negatively correlated with tumor-cell E-cad expression while positively correlated with tumor-cell N-cad expression, suggesting that extensive necroptosis contributed to HNSCC-cell EMT." (PMID 38926796, 2024). "MLKL expression in tumor tissues can possibly affect therapeutic effectiveness." (PMID 38474369, 2024). "There was hyperactivation of GSDMD, GSDME, and p-MLKL in dMMR tumor cells." (PMID 38740747, 2024). "MLKL might serve as a candidate tumor suppressor and a potential prognostic biomarker in certain types of cancers." (PMID 38474369, 2024). "The use of a PARP-1 inhibitor to block parthanatos could then restore tumor growth and immune evasion in MLKL-knockout HCC tumors." (PMID 38799433, 2024). "Additionally, when combined with a Smac mimetic LCL-161, an IAP antagonist, quercetin or kaempferol synergistically induced RIPK1/RIPK3/MLKL-mediated necroptosis in CCA cells while sparing non-tumor cholangiocyte cells." (PMID 37513508, 2023). "Importantly, pharmacological inhibition of poly(ADP-ribose) polymerase to block parthanatos restores the tumor growth and immune evasion in MLKL-knockout HCC tumors." (PMID 36650126, 2023). "On the other hand, apoptosis is accounted for the remaining tumor cell death in MLKL KO tumors." (PMID 36703228, 2023). "Furthermore, scientists from VIB-UGent Center for Medical Biotechnology have made significant progress by inducing the production of MLKL protein in cancer cells, promoting necroptosis in tumor cells, and triggering recognition by the immune system." (PMID 37169000, 2023). "Interestingly, the MLKL protein also induces the immune system to attack surviving tumor cells while mediating explicitly programmed cell death without affecting the apoptotic process." (PMID 37169000, 2023). "While Utilizing Nec-1 to treat mice or specific knockout RIPK1/MLKL could inhibit the necroptosis in endothelial cells, further decreasing tumor extravasation." (PMID 37169000, 2023). "Of note, previous studies have suggested that HSP90 can influence the activation and stability of crucial regulators involved in the necroptosis process, such asRIPK1, RIPK3 and MLKL, thereby contributing to immune cell recruitment and immunogenic cell death of tumor cells." (PMID 38149248, 2023). "Furthermore, the role of IL-8 in PDT differs from radiotherapy, in which IL-8 induces an epithelial–mesenchymal transition and tumor cell repopulation after radiotherapy via RIP1/RIP3/MLKL/JNK/IL-8 pathways, leading to a poor prognosis for cancer patients." (PMID 37239013, 2023). "Moreover, DMW also activated RIPK1, RIPK3, and MLKL axis in tumour tissues from xenograft mice, thus, suggesting a necroptotic effect." (PMID 35955595, 2022). "The higher rate of cell proliferation in NFPAs might explain the lower expression of MLKL gene and its protein level in tumor tissues of patients with NFPAs in the current study." (PMID 34983494, 2022). "Studies often indicate opposing roles for MLKL as a tumor-suppressing or a tumor-promoting protein." (PMID 35422482, 2022). "Little is known about the role of the necroptosis executioner MLKL in tumor development." (PMID 35422482, 2022). "In addition, necroptosis is involved in tumor recurrence after radiotherapy through the RIP3/RIP1/MLKL/Janus kinase (JNK)/interleukin 8 (IL-8) pathway." (PMID 36016998, 2022). "Importantly, our finding that the glucose analog, 2DG, blocks GD-induced MLKL phosphorylation in tumors suggests that glucose deprivation plays a key role in tumor necroptosis during tumor development." (PMID 33976222, 2021).
tumor (continued). "This means that MLKL might function in tumor metastasis via regulation of gene expression only in specific tumor cell types." (PMID 33754026, 2021). "Both tBID and MLKL mRNA induced significant cell death in vitro and delayed tumor growth in vivo." (PMID 33658037, 2021). "Importantly, we found that RIPK1 deletion actually increased, instead of reducing, tumor necrosis and MLKL phosphorylation in RIPK1 KO tumors." (PMID 33976222, 2021). "This suggests that low expression of MLKL may contribute to both tumor survival and regulate gene expression, thus promoting metastasis." (PMID 33754026, 2021). "Although chemotherapeutics normally trigger cell death in RIP3-/- or MLKL-/- tumor cell death via caspase-3-dependent apoptosis, it is unable to induce systemic anti-tumor response and inhibit tumor growth in vivo, which indicates necroptosis pathway plays a potential role in ICD." (PMID 33643911, 2020). "Results suggest that the MLKL expression is significantly upregulated in tumor tissues." (PMID 32444644, 2020). "However, our IHC results showed a significant correlation of MLKL and p-MLKL expression in tumor tissues, and we also observed higher “spontaneous” cell death in MLKL-overexpression cell lines." (PMID 32444644, 2020). "Moreover, the MLKL expression are positively correlated with p-MLKL expression in tumor tissues (Table." (PMID 32444644, 2020). "In addition, the in vivo pro-necroptosis effect of Sur-X was confirmed by the extensive necrosis and the reduced MLKL expression in tumor tissues from Sur-X-treated mice." (PMID 32381104, 2020). "Furthermore, immune-mediated tumor control occurred independently of MLKL, cell lysis, and DAMPs release." (PMID 32231206, 2020). "Therefore, we further analyzed the relationship between the MLKL expression, p-MLKL expression, tumor necrosis, and the patients’ prognosis." (PMID 32444644, 2020). "MLKL expression was particularly intense at the tumor invasion front." (PMID 31999765, 2020). "Therefore, to assess the extent of necroptosis contribution in the tumor necrosis, we conducted H&E and p-MLKL staining on serial sections of 40 HSNCC tumor tissues." (PMID 32444644, 2020). "Notably, RIPK1, RIPK3 and/or MLKL are downregulated in various types of cancer, reflecting the necessity for tumor cells to circumvent necroptosis." (PMID 32366830, 2020). "We then performed p-RIP3, p-MLKL, and H&E staining on serial sections of tumor tissues." (PMID 32444644, 2020). "Interestingly, we found that MLKL intensity was higher in the invasive front of tumor than in the center." (PMID 31999765, 2020). "Moreover, although both p-MLKL expression and tumor necrosis were correlated with OS and PFS in univariate analysis, the necrosis was later excluded in the multivariate cox-regression model." (PMID 32444644, 2020). "To investigate whether emodin induced necroptosis in vivo, we measured the levels of TNF-α, RIP1, RIP3 and MLKL in tumor tissues treated with emodin or saline." (PMID 30924024, 2020). "Similarly, inducing spontaneous necroptosis in subcutaneous murine tumors by overexpressing MLKL mRNA synergized efficiently with anti-PD1 immunotherapy to elicit potent anti-tumor immunity." (PMID 32752206, 2020). "In the present study, we have found a novel role of celastrol as an anti-tumor medicine through reducing the expression of BGN to activate RIP1/RIP3/MLKL signaling pathway, leading to necroptosis and decreased secretion of pro-inflammatory cytokines in HGC-27 and AGS cells." (PMID 31739592, 2019). "To further evaluate whether 10 Gy irradiation can induce the activation of MLKL in vivo, we examined the level of pMLKL using a mouse xenograft tumor derived from HT29 cells." (PMID 31706322, 2019). "Radiation-induced necroptosis depended on activation of RIP1/RIP3/MLKL pathway, and the evidence in vitro and in vivo demonstrated that the inhibition of necroptosis attenuated growth-stimulating effects of irradiated tumor cells on living tumor reporter cells." (PMID 31706322, 2019).
tumor (continued). "Western blot analysis of the xenograft tumor tissues showed that the ratio of activated MLKL (p-MLKL Ser358) to total MLKL was decreased in reconstituted wild-type NRF1 or K230R cells comparing with control cells, indicating that the necrosis in the tissues is not due to MLKL-mediated necroptosis." (PMID 30833558, 2019). "Most likely, the MLKL-mRNA treatment provokes the recruitment of T cells to the tumor bed." (PMID 31225452, 2018). "Therefore, each primary tumor’s sensitivity to complement-dependent, RIPKs/MLKL-mediated cytotoxicity will have to be assessed individually." (PMID 29527209, 2018). "Also, in this set-up, a pronounced delay in tumor growth of the untreated tumor was observed in the case of MLKL-mRNA treatment." (PMID 30143632, 2018). "However, the most striking antitumor effect was observed for intratumor treatment with MLKL-mRNA: this treatment significantly delayed tumor growth and increased the median survival time to 64 days." (PMID 30143632, 2018). "However, the idea that proteins of the core pathway of necroptotic cell death (RIPK1/3 and MLKL) can promote tumour growth has been recently published." (PMID 29434255, 2018). "Once inside the tumor bed, T cells primed by intratumor MLKL-mRNA treatment might be silenced by multiple immune-suppressive mechanisms used by tumors to evade elimination." (PMID 30143632, 2018). "This way, the tumor, if accessible for MLKL mRNA treatment, effectively becomes its own vaccine." (PMID 31225452, 2018). "Loss of MLKL showed a reduction but not significant number of tumor nodules formed in the lung compared with Ripk3−/−." (PMID 28151480, 2017). "Taken together, we conclude that pro-necroptic factors such as RIPK1, RIPK3, and MLKL may play a role in supporting tumor growth, and MLKL may be a promising target for cancer treatment." (PMID 26959742, 2016). "To clarify whether MLKL is also involved in the TRAIL/zVAD/CHX-induced killing of tumor cells, we exemplarily analyzed U-937 and HT-29 cells after downregulation of MLKL." (PMID 24507727, 2014). "To identify factors that may contribute to the immunogenicity of MLKL-driven local necroptotic tumor cell death, we performed a broad cytokine and chemokine screening within the TME of either wild-type or MLKL−/− tumors in mice undergoing checkpoint inhibitor immunotherapy." (PMID 40345706, 2025). "In addition, the higher expression of RIPK1, RIPK3, and MLKL implicates tumor necroptosis." (PMID 40739587, 2025). "Our study discovered that several antitumor drugs, such as 17-AAG, AMG900, and BOS-172722, were highly effective in patients with high expression of cross-necroptosis genes, particularly MLKL, which may overcome resistance to classical chemotherapy and enhance the anti-tumor effect." (PMID 37000317, 2023). "Hence, the expression of TNFR1 and of RIPK1/RIPK3/MLKL proteins by tumor cells, in conjunction with the production of TNFα in the tumor microenvironment, could represent novel biomarkers for cisplatin sensitivity in apoptosis-resistant tumors." (PMID 34490126, 2021). "In fact, absence of RIPK3 in cancer cells is documented to reduce the type I IFNs-mediated immune responses following treatment with chemotherapy; such that, failure to induce necroptosis (due to lack of RIPK3 or MLKL) can hamper tumor-associated immune infiltration after chemotherapy." (PMID 32752206, 2020). "Finally, MLKL/JNK/IL-8 could be potential targets for blocking tumor repopulation and improving the efficacy of radiotherapy." (PMID 31706322, 2019). "Thus, patients with low MLKL expression levels in tumor tissues may be less likely to benefit from the regular anti-tumor treatment, which results in the poor prognosis of cancer patients." (PMID 30005626, 2018).
tumor (continued). "Since the MLKL-based mRNA therapy reported here induces robust infiltration of antigen-presenting cells into the tumor, it is possible that a combination therapy with a checkpoint inhibitor could further improve the curative potential of intratumor delivery of MLKL-mRNA." (PMID 30143632, 2018). "In addition, we show that a small molecule inhibitor of MLKL could potently inhibit tumor growth in mice." (PMID 26959742, 2016). "We demonstrate that the anti-CD47 antibodies SRF231, magrolimab, and B6H12 eliminated tumor cells from various in vitro and in vivo lymphoid malignant models via the activation of the RIPK1/MLKL/necroptotic pathway." (PMID 41484790, 2026). "Under the stimulation condition of the supernatant of HER2 + IBC tumour cells, the results of the WB experiment can also confirm that RIPK1-mediated MLKL phosphorylation is involved in this process." (PMID 40624675, 2025). "Overexpression of MLKL upregulates CD47 expression via IL-6 signaling, which consequently suppresses macrophage phagocytosis and enhances tumor immune evasion." (PMID 41267084, 2025). "Studies have shown that radiation therapy significantly upregulates the expression of MLKL in tumor cells and activates the RIPK1/RIPK3/MLKL axis through the ZBP1‐mediated pathway, directing tumor cells to undergo necroptosis." (PMID 41287826, 2025). "We next evaluated protein expression profiles using data from the Clinical Proteomic Tumor Analysis Consortium, which confirmed elevated RIPK1, RIPK3, and MLKL protein abundance in GBM relative to normal tissue." (PMID 41429922, 2025). "MLKL-mRNA therapy further exemplifies this synergy, as its combination with ICB leads to enhanced CD8+ T cell-mediated tumor clearance and the establishment of durable immune memory." (PMID 41235238, 2025). "In pancreatic ductal adenocarcinoma (PDAC), MLKL has been observed to enhance CD47-SIRPα signaling in tumor cells, which in turn inhibits macrophage phagocytosis and enables tumor cells to evade immune clearance." (PMID 39575419, 2024). "Shikonin (SHI), a natural compound extracted from a Chinese herb, can mediate necroptosis to inhibit tumor growth by promoting RIPK3 phosphorylation, which subsequently promotes MLKL phosphorylation." (PMID 38684668, 2024). "During tumor prognosis, it has been shown that necroptosis promotes tumor repopulation after the treatment through RIP1/RIP3/MLKL/JNK/IL8 signaling pathway." (PMID 38575922, 2024). "Tumor cells developed various machineries including oncogene-driven, epigenic, transcriptional, and post-translational regulation of RIP3 and MLKL to form necroptotic resistance." (PMID 38926796, 2024). "Also, similarly to what was observed for MLKL, we have previously shown that higher RIPK3 expression is associated with worse prognosis in diffuse glioma patients, suggesting that increased sensitivity to necroptosis may be also relevant to tumor progression." (PMID 37651429, 2023). "MLKL, along with RIPK1 and RIPK3, induce neutrophil extracellular traps, allowing them to act as a physical barrier to protect tumor cells from T or NK cell-mediated cytotoxicity." (PMID 37864090, 2023). "Most human tumor cell lines have a defect in RIPK3 expression and consequently fail to induce necroptosis as measured by MLKL phosphorylation." (PMID 36768641, 2023). "Importantly, these alterations were abolished when tumors were subcutaneously implanted in the immune-competent mice, which echoed the tumor growth phenotypes and suggested that the enhanced anti-tumor immune response in the liver may account for the impeded tumor growth upon MLKL depletion." (PMID 36650126, 2023). "Surprisingly, in the majority of cancers, both RIPK3 and MLKL promoted tumor immune cell infiltration, particularly in BUC where MLKL increased the infiltration of neutrophils, which supports previous findings that necroptosis can boost antitumor immunity." (PMID 37000317, 2023).
tumor (continued). "Here, we demonstrate that MLKL act as an independent prognostic biomarker in LGG similarly to RIPK3 and supports the rationale that increased tumor expression of necroptotic molecules is detrimental to these patients." (PMID 37651429, 2023). "Conversely, MLKL and CASP8 were significantly lower in tumor tissues compared to normal tissues (KIRC BLCA LUSC LUAD, etc.)." (PMID 37000317, 2023). "The inhibitory effects of radiotherapy on tumor growth in the MC38 mouse colon adenocarcinoma cell line and B16-SEY mouse melanoma cell line are directly related to the expression of MLKL in tumor cells, via ZBP1-mediated necroptosis signal transduction." (PMID 36615244, 2022). "Immunohistochemical analyses showed that IBC induced a substantial increase in RIP3 and MLKL and activated the RIP1-RIP3-MLKL pathway in the MDA-MB-231 derived tumor." (PMID 36296386, 2022). "In this study, MLKL mRNA electroporation in vivo was demonstrated to induce CD4+ and CD8+ T cell responses directed against tumor antigens that were responsible for tumor control." (PMID 34490126, 2021). "MLKL was also mainly immunolocalized in the cytoplasm of CCA tissues, normal cholangiocyte adjacent to tumor tissues, and cholangiocytes in normal liver tissues." (PMID 34083572, 2021). "Emodin significantly reduced tumor growth promoting necroptosis, as demonstrated by the increased levels of TNF-α (tumor necrosis factor α), RIP1, RIP3, and MLKL (mixed lineage kinase domain-like protein) observed in tumor tissues of the emodin-treated group." (PMID 34068184, 2021). "Based on the critical tumor-suppressive function of RIPK3 during leukemogenesis, we determined the role of its downstream effector MLKL in AML." (PMID 34079078, 2021). "In SCCs, tumor tissues had significantly lower mRNA expression level of RIPK1 (P = 5 × 10-4), RIPK3 (P = 3 × 10-15), and MLKL (P = 1 × 10-5) compared to normal lung tissues." (PMID 32742497, 2020). "Therefore, high expression of MLKL at the tumor invasion front may induce necroptosis." (PMID 31999765, 2020). "In this study, moreover, patients with low tumor expression of RIPK1, RIPK3, and MLKL proved to have worse DFS." (PMID 32742497, 2020). "Additionally, the authors also reported that the higher phosphorylation levels of MLKL were correlated with a poorer prognosis and shorter survival in human patients with colon and esophageal cancer, indicating that necroptotic genes play a critical role in tumor promotion." (PMID 31122251, 2019). "MLKL-mRNA treatment rapidly induces T cell responses directed against tumor neo-antigens and requires CD4+ and CD8+ T cells to prevent tumor growth." (PMID 30143632, 2018). "Resibufogenin retards tumor growth and metastasis by activating RIP3 and subsequently phosphorylating MLKL which lead to necroptosis." (PMID 30029665, 2018). "As we observed that during clonogenic and soft agar growth experiments, RIPK3-, RIPK1-, or MLKL- knockout cells tend to have significantly smaller colonies, we hypothesized that the necroptotic genes may regulate important cytokines required for tumor cell growth." (PMID 26959742, 2016). "Regardless of the RIPK3 status in tumor cells, using optogenetically activatable MLKL can still trigger the release of both cDAMPs and iDAMPs, demonstrating its ability to elicit an immune response independent of upstream RIPK3 signaling." (PMID 39921454, 2025). "Consistently, IHC analysis of HN12 tumor tissues isolated from the NSG xenograft mouse models subjected to mock, wtVSV or VSV-S infection revealed significantly elevated levels of IL-1β and p-MLKL in both wtVSV- and VSV-S-infected groups." (PMID 39789615, 2025). "Necroptosis plays dual roles in cancer: it acts as a tumor suppressor in colorectal and hepatocellular carcinomas, where RIPK3/MLKL downregulation correlates with poor prognosis, but may promote inflammation-driven malignancy in specific contexts." (PMID 41235238, 2025).